CRP (C-reactive protein)
Diseases named in the same sentence as CRP in open-access papers (continued):
Sharing a sentence is not in itself a finding about the gene and the disease.
pneumonia (continued). "Furthermore, they presented significantly more often with fever (91.2% vs. 60.6%; p < 0.0001), a septic appearance (48.5% vs. 30%; p = 0.0002), pneumonia (76.8% vs. 39.1%; p < 0.0001), acute otitis media (26.5% vs. 10%; p < 0.0001), and a higher CRP on admission (26.9 mg/L vs. 4.3 mg/L; p < 0.0001)." (PMID 32807104, 2020). "In conclusion, although it is likely that other factors may affect the decision making, e.g. anamnestic details, clinical examination findings, or the impression of the patient’s general health condition, this study suggests that CRP result highly influences the degree of suspicion of pneumonia." (PMID 33399009, 2020). "Therefore, when Xuebijing is used to treat severe pneumonia, gender may be an influencing factor in the change of CRP level." (PMID 32908573, 2020). "The increasing use of both CRP and microbiological tests in diagnosing pneumonia might reflect the absence of clear diagnostic criteria and possibly a perceived need for diagnostic tests in primary care." (PMID 32127365, 2020). "The significantly higher CRP in the fall group without a hip fracture is most likely caused by the fact that the admission was not only indicated by the fall but also by inflammatory diseases such as pneumonia or infection of the urinary bladder." (PMID 32411473, 2020). "However, most patients had a CRP test performed (pneumonia: 83.1%; acute bronchitis: 71.4%)." (PMID 31650886, 2020). "Thus, an increase of 10 mg/L of CRP increases the likelihood (odds) of pneumonia by 30%." (PMID 26937636, 2016). "Moreover, we found no marked increase in C-reactive protein, and no cases of bacteremia or pneumonia, caused by probiotic use in the patients, which confirmed that the probiotics used in this study were safe for use in patients with H7N9 infection." (PMID 24990477, 2014). "CRP levels in that study were unrelated to pneumonia risk, though the CRP assay used in that study was not a newer high-sensitivity assay such as the one we used, so their CRP data may have been compromised to some degree." (PMID 23457535, 2013). "These cases were more likely to have a high neutrophil count and a high CRP, compared to other pneumonia cases where RSV was detected (OR 2.3, 95% CI 1.5–3.5, p<0.001), implying that these cases represented a bacterial superinfection of RSV associated pneumonia." (PMID 23320118, 2013). "Therefore, we conducted a prospective study with the aim of assessing whether ICS usage in patients with COPD increased the rate of pneumonia, and whether PlGF and CRP could predict the development of pneumonia in patients with COPD using ICS." (PMID 21962211, 2011). "We demonstrated in an earlier diagnostic study that for patients with a CRP less than 20 mg/l and who had no more than 1 of the 3 clinical predictors of pneumonia (dry cough, fever, diarrhoea), the absolute risk of pneumonia was reduced from 13% to less than 3%." (PMID 17394651, 2007). "Our findings therefore suggest that CXR-confirmed pneumonia coupled with serological markers of CRP and procalcitonin is a more specific marker of pneumococcal pneumonia and may therefore provide a closer estimate of the efficacy of the PnCV against pneumococcal pneumonia." (PMID 15736995, 2005). "The specificity of CXR-confirmed pneumonia as an outcome measure of efficacy of PnCV to prevent pneumococcal pneumonia was improved when it was analysed together with indirect evidence suggestive of bacterial infection, namely, elevated CRP and procalcitonin levels." (PMID 15736995, 2005). "In infants with severe disease: serum procalcitonin and c-reactive protein testing at ICU admission had some benefit in predicting bacterial co-infection and/or pneumonia (very low quality evidence)." (PMID 41906981, 2026). "CRP and PCT levels are related to the severity of chronic obstructive pulmonary disease complicated with pneumonia." (PMID 41509129, 2026).
pneumonia (continued). "Where the physicians diagnosed pneumonia, the SARS-CoV-2 POCT was used in 80.1% of consultations, and the CRP test in 80.9%." (PMID 40739482, 2025). "Initial investigations demonstrated severe hyponatraemia, elevated C-reactive protein, and left-basal consolidation on chest X-ray, along with a subsequent diagnosis of syndrome of inappropriate ADH secretion (SIADH) due to pneumonia." (PMID 41458663, 2025). "The study finds that patients with severepsittacosis pneumonia have elevated levels of white blood cells (WBCs),neutrophils, neutrophil-to-lymphocyte ratio (NLR), C-reactive protein(hs-CRP), and procalcitonin (PCT), as well as a higher detection rate offungi." (PMID 40990897, 2025). "The results demonstrated that mechanical ventilation (OR = 4.80), CRP (OR = 1.12), PCT (OR = 1.65), IL-6 (OR = 1.11), and IgA (OR = 0.02) were the independent influencing factors for ACD in children with severe pneumonia." (PMID 41234411, 2025). "These were incorporated into a Logistic regression model, which revealed that mechanical ventilation, CRP, PCT, IL-6, and IgA were influencing factors for ACD in children with severe pneumonia." (PMID 41234411, 2025). "Previous studies have shown that critically ill patients exhibit significantly higher levels of PCT, CRP, and lactate dehydrogenase (LDH), whereas patients with severe pneumonia have significantly lower albumin levels." (PMID 40247166, 2025). "It is worth noticing that CRP and proGRP concentrations were higher in COPD-E and pneumonia cases while in ADC and SQCC they were lower." (PMID 39703761, 2025). "While the risk for hospitalization is low with Omicron, our data from hospitalized patients with high Omicron viral loads or pneumonia show that patients may benefit if (isotonic) SNI and saline gargling are started early; this is associated with increases in lymphocytes and a reduction in CRP." (PMID 40910061, 2025). "Based on the RF model, the importance scores of independent influencing factors for the clinical efficacy of BAL in the treatment of severe pneumonia were calculated, and the importance ranking was as follows: PaO2, PCT, age, PaCO2, CRP, and comorbid COPD." (PMID 41574374, 2025). "Elevated C-reactive protein (CRP) levels typically indicate inflammation, with conditions like pneumonia, COPD exacerbations, and asthma showing increased CRP levels due to the inflammatory response in lung tissue (Póvoa, 1998)." (PMID 41395368, 2025). "C‐reactive protein (CRP), procalcitonin (PCT), suPAR, CURB‐65 and Pneumonia Severity Index (PSI) scores were measured at admission, and patients were followed for 365 days." (PMID 40523722, 2025). "Necrotizing Pneumonia (n = 4): Most (75%) had elevated WBC and neutrophils, platelets were normal, and half had positive CRP and ESR." (PMID 41294904, 2025). "This theory is supported by literature linking elevated inflammatory biomarkers like CRP and the neutrophil-to-lymphocyte ratio (NLR) to worse outcomes in pneumonia." (PMID 41552206, 2025). "The prediction nomogram model, based on 6 common clinical and laboratory test variables (pneumonia, EVD, tracheotomy, PCT, CRP, and Alb), was able to easily and accurately predict ICI after intracranial aneurysm surgery." (PMID 40529435, 2025). "Given the well-established link between pneumonia, systemic inflammation, and atrial arrhythmias, routine ECG monitoring may be warranted in high-risk pneumonia patients, particularly those with elevated CRP, pre-existing cardiovascular disease, or electrolyte disturbances." (PMID 40151738, 2025). "For example, for patients with severe pneumonia admitted to the emergency department, if HBP > 55.9 ng/mL (the cut-off value in this study), even if PCT and CRP are normal, it is necessary to initiate broad-spectrum antibiotic therapy and fluid resuscitation." (PMID 41293058, 2025).
pneumonia (continued). "Clinical data and laboratory parameters (white blood cell count, neutrophil-to-lymphocyte ratio, high-sensitivity C-reactive protein, and lactate dehydrogenase) were retrospectively analyzed in 112 ADV pneumonia cases (2022) and 175 cases (2023)." (PMID 40742118, 2025). "In terms of inflammatory markers, LDH and CRP of the MPP group and the Bacterial Pneumonia group were compared with the healthy control group, and the difference was statistically significant (P < 0.05)." (PMID 40460103, 2025). "The prediction model based on respiratory rate, weight, CRP, NEU, HGB, UA, and BUN has shown promising predictive value in distinguishing between mild to moderate pneumonia and severe pneumonia in neonates." (PMID 40529154, 2025). "This study found that CRP, PCT, and LYM were the key factors for predicting poor prognosis in severe pneumonia cases." (PMID 40529154, 2025). "This study investigated the effects of N-Acetylcysteine (NAC) combined with Ambroxol Hydrochloride (AH) on clinical symptoms, C-Reactive Protein (CRP), and Procalcitonin (PCT) levels in children with pneumonia." (PMID 39208656, 2024). "The prognostic assessment tools usually used are the pneumonia severity index (PSI) and CURB-65, as well as routine inflammatory biomarkers such as C-reactive protein (CRP) and procalcitonin (PCT)." (PMID 39182045, 2024). "Examining the changes in CRP serum values in patients with measles hospitalized at the Clinic for Infectious Diseases, University Clinical Center, Niš, we detected an association between the symptom severity (pneumonia category) and not with the changes detected on the chest X-ray." (PMID 39064460, 2024). "In the “New Coronavirus Pneumonia Diagnosis and Treatment Program (Trial Version 10),” PCT, CRP, IL-6, and other indicators are regarded as early warning indicators for disease deterioration." (PMID 39533550, 2024). "Recent studies have demonstrated that levels of C-reactive protein (CRP), a crucial inflammatory factor, are correlated with early-onset pneumonia (EOP) in ECPR patients." (PMID 39583157, 2024). "The physiological fluctuation of CRP and PCT in infants is relatively large, and there is a lag in the prognosis evaluation of severe pneumonia." (PMID 39411281, 2024). "The AUC value for NSE diagnosis of pneumonia is 0.714; The AUC value for CRP diagnosis of pneumonia is 0.539; The AUC value for ESR diagnosis of pneumonia is 0.535." (PMID 38822291, 2024). "It was demonstrated that pneumonia patients with bacterial/mixed origin have higher levels of WBC and CRP compared to those of atypical or viral origin." (PMID 38183438, 2024). "The group with pneumonia-related bacteremia exhibited higher rates of CKD, CRP, PCT, IL-6 levels, and infection rates with other bacteria than the pneumonia-only group, while PA levels were lower (all p ≤ 0.05)." (PMID 37768395, 2023). "The addition of CRP (SHR, 1.17; 95% CI, 1.06–1.28) to the clinical model improved the clinical model fit (AIC value 4960 to 4950) and discrimination of pneumonia events (C-statistic 0.62 to 0.64)." (PMID 38105941, 2023). "Among the possible effects of the disease, the levels of PO2/FiO2 resulted in being significantly lower in the pneumonia group, while IL-6, CRP, rate of admission to ICU, and death were higher among the patients with pneumonia." (PMID 37631910, 2023). "Various studies have reported a correlation between reduced LVGLS, troponin and C-reactive protein (CRP) levels, and severity of pneumonia during hospitalisation for COVID-19 infection; however, these correlations were not confirmed in other studies." (PMID 37103058, 2023). "Postoperative white blood cell (WBC), C-reactive protein (CRP) levels, and prevalence of postoperative complications (i.e., pneumothorax, pulmonary atelectasis, pneumonia, wound infection, and dehiscence) were also determined." (PMID 37705106, 2023).
pneumonia (continued). "In influenza pneumonia (H1N1, H7N9), a high CRP value also correlated with disease severity, proving to be an independent predictor of mortality in the H7N9 infection, while leading to the cytokine storm characterized by elevated IL-6, MCP-1, and IP-10 levels." (PMID 37388734, 2023). "Biomarkers obtained from poststroke blood samples, such as WBC, CRP, PCT, and copeptin, were all independent predictors of pneumonia, UTI, and other infections." (PMID 37218981, 2023). "It is worth mentioning that, in our study, CRP, PCT, LDH, and NLR, in line with other investigations, were also good predictors for SARS-CoV-2 pneumonia outcome." (PMID 37959236, 2023). "It confirms that the combined analysis of WBC, Neut, CRP, and PCT is significantly effective in improving the accuracy of pneumonia diagnosis in medicine." (PMID 37292095, 2023). "Our study revealed that BMI, hs-CRP, LDH, ferritin, and Ct values were related to developing pneumonia, which correlated with a recent study." (PMID 37374302, 2023). "IL-6, WBC, L, N, CRP, PCT, PT, DD, BS, AST, ALB, D-Bil, BNP, LDH, and CK-MB differed significantly between moderate and severe pneumonia sets both in training and validation sets (P < 0.05)." (PMID 37950171, 2023). "In a model adjusted for clinical variables, baseline GDF-15 (SHR, 1.32; 95% CI, 1.02–1.69), MMP-8 (SHR, 1.14; 95% CI, 1.01–1.30) and CRP (SHR, 1.16; 95% CI, 1.06–1.27) remained significant predictors of pneumonia." (PMID 38105941, 2023). "In the infectious disease context, the most routinely used biomarkers in clinical practice and also the most commonly studied in pneumonia are PCT and CRP." (PMID 36671362, 2023). "sTREM-1 was also significantly better than PCT and CRP for the outcome of all in-hospital mortality for children with IMCI pneumonia and severe pneumonia." (PMID 35830474, 2022). "Therefore, a SARS-CoV-2 positive PCR test, in combination with symptoms, significantly elevated the laboratory parameters (CRP, NLR, LDH) and radiological findings of pneumonia, and may refer to patients at risk of developing arterial thrombosis, and thus, urgent CTA diagnosis is necessary." (PMID 35329864, 2022). "Medically, examination criteria such as C-reactive protein (CRP) levels can be employed in the early diagnosis of pneumonia, and patients presented with severe pneumonia had high CRP levels." (PMID 36135003, 2022). "By comparing with CRP or S1P, combining CRP and S1P had significantly higher AUC value for differentiating between the COPD with pneumonia group and the AECOPD group (p < 0.001 and p < 0.005, respectively)." (PMID 35307030, 2022). "Our study demonstrated that the development of pneumonia in mechanically ventilated patients (VAP) depends on numerous factors, including multi-organ injury, albumin and leucocytes levels, the CRP value, an age over 61 years, and the male gender." (PMID 35010870, 2022). "We therefore conducted this study to assess the value of IL-6 in the diagnosis of early pneumonia after cardiac surgery and compare it with that of PCT, CRP and WBC counts." (PMID 35794529, 2022). "The use of conventional diagnostic markers, such as complete blood count with differential and C-reactive protein (CRP), is the current mainstream method for differentiating clinically relevant pneumonia from other mimics." (PMID 35307030, 2022). "Further studies should be carried out to investigate the use of other novel inflammatory markers, such as CRP and PCT, in critically ill patients with pneumonia." (PMID 36153405, 2022). "Among all the variables tested in our prediction models, biomarkers such as CRP and PCT demonstrated the most significant discriminating power in the prediction of pneumonia." (PMID 35968461, 2022). "For the three patients with pneumonia who were admitted to the ICU, the mean CRP value on the first day was 12.23 mg/L." (PMID 36676040, 2022).
pneumonia (continued). "Pneumonia cases showed increased IL-6 levels compared with pure DAD cases, whereas CRP levels were weaker discriminators." (PMID 35992303, 2022). "By comparing with CRP or S1P, combining CRP and S1P had significantly higher AUC value for differentiating between the COPD with pneumonia group and the AECOPD group." (PMID 35307030, 2022). "Laboratory findings in patients with X-ray confirmed pneumonia showed a four times higher neutrophil-to-lymphocyte ratio (NLR), C-reactive protein (CRP) and three times higher lactate dehydrogenase level (LDH) than patients without confirmed pneumonia." (PMID 35329864, 2022). "Plasma fetuin-A levels were negatively correlated with WBC, NE%, Glu, CRP, PCT, CURB-65, and pneumonia severity index scores and positively correlated with albumin level." (PMID 35966877, 2022). "There has been some research into predicting Severe Mycoplasma Pneumoniae Pneumonia (SMPP) primarily focused on pre-treatment time by macrolide, pre-hospital course, CRP and LDH et.al." (PMID 35498793, 2022). "CRP and PCT, which are the severity indexes of pneumonia, were higher in co-infection patients, suggesting that co-infection of H1N1 and SARS-CoV-2 is more severe than monoinfection by SARS-CoV-2." (PMID 34843492, 2021). "Higher proportion of patients with wheezing, rales and severe pneumonia, and higher levels of LDH, AST, ALT and CRP were found in patients with HBoV co-infected with bacteria." (PMID 34715898, 2021). "Results: 1608 patients with severe influenza pneumonia with PCT and CRP available levels on admission were included, 1186 with primary viral pneumonia (PVP) and 422 with bacterial Co-infection (BC)." (PMID 33810263, 2021). "The first component represents 26.6% of the data variability and was correlated to initial severity (SOFA score, pneumonia severity index (PSI)) and acute phase response (CRP)." (PMID 34031519, 2021). "Currently, CRP and PCT were explored for their clinical values in the management of pneumonia, but their utilization was challenged due to the accuracy." (PMID 34558385, 2021). "In a large retrospective study, serum high-sensitivity CRP (hs-CRP) level (cut-off value, 61 mg/L) at admission was more useful than PCT in the diagnosis of pneumonia in hospitalized elderly patients." (PMID 34344141, 2021). "Among traditional biomarkers of inflammation, C-reactive protein (CRP) and procalcitonin (PCT) are the most frequently used for prognostication of pneumonia in adults." (PMID 35011845, 2021). "For example, potentially useful biomarkers for severe or refractory pneumonia include AST, ALT, LDH, CRP, ferritin, and various cytokines (IL-18, IL-6, or TNF-α)." (PMID 33810090, 2021). "The following variables were predictive of mortality in the univariate analyses: age, atrial fibrillation, insulin-dependent diabetes (IDDM), C-reactive protein (CRP), supplemental oxygen requirement, pneumonia on initial radiology, and ischemia." (PMID 34270604, 2021). "Besides, several studies have illustrated that CRP could be used to assist pneumonia diagnosis, thus we consequently combined CRP, age and clinical signs to build a new multivariate screening model and compared its discriminating ability with our integrated model using LMR and NLR." (PMID 34861849, 2021). "An explanation could be the fact that CRP is a systemic parameter influenced by other systemic conditions or inflammations (autoimmune disorders (e.g. rheumatoid arthritis), other infectious foci (e.g. bronchitis, pneumonia, urinary tract infections) or cancer) misleading the diagnosis of PJI." (PMID 33247312, 2021). "Accuracy of traditional (CRP, PCT) and newly proposed biomarkers (SAA, NP) and ratios of CRP/NP and SAA/NP was too low to help diagnosing pneumonia in the elderly." (PMID 32997689, 2020). "Some multivariate regression analysis had found that serum levels of CRP and PCT were strong predictors for the severity of pneumonia." (PMID 33294084, 2020).